SSR4 (signal sequence receptor subunit 4)
Description:
TRAP proteins are part of a complex whose function is to bind calcium to the ER membrane and thereby regulate the retention of ER resident proteins.
Synonyms: TRAPD; CDG1Y
Tractability: Antibody: UniProt predicts a signal peptide or a membrane-spanning region. PROTAC: UniProt records ubiquitination sites on it; ubiquitination databases record sites on it; its protein half-life has been measured.
Gene: Protein-coding gene on chromosome X (153,793,516 to 153,798,505, forward strand). Ensembl gene ENSG00000180879.
Subcellular location: Endoplasmic reticulum membrane
Subcellular location (Human Protein Atlas): Endoplasmic reticulum
Pathways (Reactome):
Metabolism of proteins: SRP-dependent cotranslational protein targeting to membrane
Gene Ontology:
Biological process: post-translational protein targeting to membrane, translocation
Cellular component: endoplasmic reticulum; extracellular exosome; endomembrane system; endoplasmic reticulum membrane; Sec61 translocon complex; translocon complex; membrane
Homologues: Orthologues: chimpanzee SSR4 (100% identical), macaque SSR4 (99% identical), dog SSR4 (98% identical), rabbit SSR4 (97% identical), mouse Ssr4 (95% identical), guinea pig SSR4 (90% identical), rat Ssr4 (89% identical), pig SSR4 (88% identical), tropical clawed frog ssr4 (71% identical), zebrafish ssr4 (68% identical), Drosophila melanogaster Tapdelta (32% identical), Caenorhabditis elegans trap-4 (29% identical).
Diseases named in the same sentence as SSR4 in open-access papers:
SSR4 is named in the same sentence as 30 diseases in open-access papers, as found by Europe PMC text mining. Sharing a sentence is not in itself a finding about the gene and the disease. The quoted sentences say what the papers report.
congenital disorder of glycosylation (3 papers, 2020 to 2025). Congenital disorder of glycosylation (CDG) is a fast growing group of inborn errors of metabolism characterized by defective activity of enzymes that participate in glycosylation (modification of proteins and other macromolecules by adding and processing of oligosaccharide side chains). "Mutations in SSR4 are linked to specific congenital glycosylation disorders, which can manifest as developmental delay, intellectual disabilities, and various physical abnormalities." (PMID 40066443, 2025). "Diseases associated with SSR4 mutations include two types of congenital glycosylation disorders." (PMID 40066443, 2025). "In addition, TRAP may play a role during unfolded protein response, endoplasmic-reticulum-associated protein degradation and congenital disorder of glycosylation (ssr4 CDG)." (PMID 32453970, 2020). "Recently, mutations in the human TRAPγ and TRAPδ subunits (SSR3 and SSR4, respectively) were found to result in loss of TRAP and congenital disorders of glycosylation (CDG), suggesting that TRAP plays a direct or indirect role in the biogenesis of N-glycosylated proteins (MIM 300090 and 606213)." (PMID 33925740, 2021).
developmental delay (3 papers, 2024 to 2025). "Disruption of SSR4 is now known to cause congenital disorder of glycosylation type 1 y (CDG1Y; OMIM #300934) an X-linked disorder characterized by developmental delay, muscular hypotonia, microcephaly, and distinctive facial features." (PMID 40662097, 2025). "Pathogenic mutation of SSR4 can induce SSR4-CDG, whose major clinical symptoms include developmental delay, respiratory distress, feeding difficulty in infancy, appearance deformity (e.g., microcephalus, micrognathia, macrotia, deep-set eyes, etc.), and hypotonia." (PMID 39086474, 2024).
Congenital disorders of glycosylation type Iy (2 papers, 2025 to 2026). "Hemizygous variants in the SSR4 gene cause congenital disorder of glycosylation, type Iy (CDG1Y, OMIM 300934), also called SSR4-CDG." (PMID 41210240, 2025). "SSR4 gene was related with Congenital disorder of glycosylation, type Iy (CDG1Y, OMIM 300934)." (PMID 41210240, 2025).
CHARGE syndrome (1 paper, 2024). CHARGE syndrome is a multiple congenital anomaly syndrome characterized by the variable combination of multiple anomalies, mainly Coloboma; Choanal atresia/stenosis; Cranial nerve dysfunction; Characteristic ear anomalies (known as the major 4 C's). "Seven infants with CHD also had genetic or syndromic diagnoses confirmed postnatally: five with 22q11.2 deletion (PA × 1, ToF × 2, Truncus arteriosus × 1, IAA × 1); one with CHARGE syndrome (ToF); and one with an SSR4 gene variant associated with X-linked disorder of glycosylation (CoA)." (PMID 39429246, 2024).
colitis (1 paper, 2026). Inflammation of the colon. "B-cell-specific Ssr4 deletion leads to peripheral B-cell loss, reduced antibody output, exacerbated colitis, and impaired mucosal immunity." (PMID 42159884, 2026).
colon adenocarcinoma (1 paper, 2025). "The SSR4 is overexpressed in immune cells of the tumor microenvironment (TME) in colon adenocarcinoma and gastric cancer and may serve as a prognostic biomarker that can predict better overall survival (OS) and therapeutic efficiency in patients with colon adenocarcinoma." (PMID 40066443, 2025).
colon tumors (1 paper, 2025). "However, although SSR4 was highly expressed in colon tumors, no significant prognostic significance was observed in this study." (PMID 40066443, 2025).
esophageal squamous cell carcinoma (1 paper, 2025). Esophageal squamous cell carcinoma (ESCC) is a type of esophageal carcinoma (EC) that can affect any part of the esophagus, but is usually located in the upper or middle third. "Relationship between signal sequence receptor subunit delta (SSR4) expression in esophageal squamous cell carcinoma (ESCC) and clinicopathological parameters." (PMID 40066443, 2025). "Univariate and multivariate Cox analysis: correlation between signal sequence receptor subunit delta (SSR4) expression and the clinical characteristics of esophageal squamous cell carcinoma (ESCC) patients." (PMID 40066443, 2025).
lymph node metastasis (1 paper, 2025). "SSR4 expression was related to the N stage, lymph node metastasis, and AJCC TNM classification stage." (PMID 40066443, 2025).
periodontitis (1 paper, 2018). An acute or chronic inflammatory process that affects the tissues that surround and support the teeth. "The immunohistochemical analysis confirmed that SSR4, MZB1 and XBP1 proteins were expressed in gingival tissue from patients with periodontitis." (PMID 29921943, 2018). "The levels of the four most highly up-regulated genes, IGLL5, SSR4, MZB1 and XBP1, were investigated in gingival RNA samples from ten subjects (six with periodontitis and four healthy controls)." (PMID 29921943, 2018).
infection (6 papers, 2009 to 2026). The state of being infected such as from the introduction of a foreign agent such as serum, vaccine, antigenic substance or organism. "In summary, our study successfully elucidated the interactions between the Mut domains of the E2 protein and host cell protein, predicted the potential pathways implicated in these interactions, and demonstrated SSR4 involvement in APPV infection." (PMID 39202352, 2024). "Previously, coding genes of Ssr4 and Rei1 were increasingly upregulated during host infection by B. bassiana." (PMID 33758028, 2021). "Revealed in our previous transcriptomic analysis, an orthologous Ssr4-coding gene was increasingly upregulated in the first 48-h infection course of Beauveria bassiana against the larvae of Plutella xylostella, a cosmopolitan lepidopteran pest." (PMID 32317391, 2020). "In this study, however, complete abolishment of cuticle infection by the ssr4 deletion is unlikely an outcome from a limited decrease in total activity of secreted enzymes involved in cuticle degradation." (PMID 32317391, 2020). "Conversely, in C. albicans SC5314 infection, ARRB2 with the same epigenetic modification triggers different proteins such as SSR4 and C18orf8." (PMID 30769958, 2019). "We demonstrate that the viral non-structural protein Nsp2 physically interacts with SSR4 via its PLP2 and hypervariable domains and selectively upregulates its expression during infection by prolonging its protein half-life." (PMID 42023815, 2026).
tumor (3 papers, 2022 to 2026). "The data indicated that SSR4 is overexpressed in tumor plasma cells than in other types of cells and it is associated with the regulation of TME, such as immune cells." (PMID 40066443, 2025). "While we have found a significant correlation between SSR4 and the tumor immune microenvironment, the direct involvement of SSR4 in regulating glucose metabolism within this context remains to be elucidated." (PMID 40066443, 2025). "Focusing on the SSR4+ and SSR4- cell subtypes, SSR4 expression levels were closely related to the interaction patterns that existed between tumor plasma cells as well as other cell subtypes, especially in the MIF/CD74/CXCR4 pathway." (PMID 40066443, 2025). "To investigate the probable implication of SSR4 in tumor plasma tissues, we isolated tumor plasma cell populations and analyzed the interplay between SSR4 expression and biological functions." (PMID 40066443, 2025). "CellChat analysis revealed different interaction patterns between SSR4+ and SSR4- subsets in ESCC tumor plasma cell populations and other cells in the TME of ESCC." (PMID 40066443, 2025). "No evident associations were recognized between age, sex, tumor morphology, T stage, M stage, and SSR4 expression (P > 0.05), but were related to N stage (P < 0.001), LNM (P < 0.001), and AJCC TNM stage (P < 0.001)." (PMID 40066443, 2025). "The SSR4 gene may have significant relevance with clinical pathological factors, and play a critical role in the regulation of tumor microenvironment of ESCC patients." (PMID 40066443, 2025). "Specifically, since the SSR4 gene has been explored in tumor plasma cells, the interaction between plasma cells and squamous epithelial cells requires further exploration, such as co-culturing plasma cells with squamous epithelial cells and knocking down the key gene." (PMID 40066443, 2025). "The SSR4 gene may play a critical role in the regulation of the tumor microenvironment of ESCC patients." (PMID 40066443, 2025). "The highest SSR4 expression was recognized in tumor plasma cells." (PMID 40066443, 2025). "Notably, the highest SSR4 expression was recognized in tumor plasma cells." (PMID 40066443, 2025). "Differentiation between SSR4+ and SSR4- cells suggests that SSR4 might regulate the interactions between ESCC tumor plasma cells and TME, possibly by modulating the MIF/CD74/CXCR4 axis." (PMID 40066443, 2025). "On dividing cells into SSR4-positive and -negative groups, CellChat analysis indicated that SSR4 may regulate the interactions that existed between ESCC tumor plasma cells and the tumor microenvironment (TME) by modulating the MIF/CD74/CXCR4 axis." (PMID 40066443, 2025).
cancer (2 papers, 2022 to 2025). A tumor composed of atypical neoplastic, often pleomorphic cells that invade other tissues. "An IHC study was conducted on 112 ESCC tissues and 68 para-cancer tissues from the tissue microarray, demonstrating significantly increased SSR4 expression in ESCC tissues (P < 0.0001) compared to normal tissues." (PMID 40066443, 2025). "Currently, there is no literature elaborating on how the SSR4 gene directly regulates the cancer microenvironment in ESCC." (PMID 40066443, 2025).
gastrointestinal disease (1 paper, 2024). A disease that occurs in the gastrointestinal system, excluding the hepatobiliary system. "SSR4 was first identified in congenital disorders of glycosylation patients, and SSR4 mutation leads to gastrointestinal diseases and abnormal glycosylation of serum transferrin levels in congenital disorders." (PMID 39872215, 2024).
SSR4 also shares sentences with these, for which no sentence is quoted: colorectal cancer (2 papers); Autoimmunity (1); chronic periodontitis (1); fructose intolerance (1); fungal infection (1); gastric cancer (1); glioblastoma (1); hematological malignancies (1); intellectual disabilities (1); intraepithelial neoplasia (1); lung adenocarcinoma (1); microcephaly (1); Obesity (1); systemic sclerosis (1); Truncus arteriosus (1); type 2 diabetes (1).